HDAC1 (histone deacetylase 1)
Description:
Histone deacetylase that catalyzes the deacetylation of lysine residues on the N-terminal part of the core histones (H2A, H2B, H3 and H4). Histone deacetylation gives a tag for epigenetic repression and plays an important role in transcriptional regulation, cell cycle progression and developmental events. Histone deacetylases act via the formation of large multiprotein complexes. Acts as a component of the histone deacetylase NuRD complex which participates in the remodeling of chromatin. As part of the SIN3B complex is recruited downstream of the constitutively active genes transcriptional start sites through interaction with histones and mitigates histone acetylation and RNA polymerase II progression within transcribed regions contributing to the regulation of transcription. Also functions as a deacetylase for non-histone targets, such as NR1D2, RELA, SP1, SP3, STAT3, ZNF76 and TSHZ3. Deacetylates SP proteins, SP1 and SP3, and regulates their function. Component of the BRG1-RB1-HDAC1 complex, which negatively regulates the CREST-mediated transcription in resting neurons. Upon calcium stimulation, HDAC1 is released from the complex and CREBBP is recruited, which facilitates transcriptional activation. Deacetylates TSHZ3 and regulates its transcriptional repressor activity. Deacetylates 'Lys-310' in RELA and thereby inhibits the transcriptional activity of NF-kappa-B. Deacetylates NR1D2 and abrogates the effect of KAT5-mediated relieving of NR1D2 transcription repression activity. Component of a RCOR/GFI/KDM1A/HDAC complex that suppresses, via histone deacetylase (HDAC) recruitment, a number of genes implicated in multilineage blood cell development (By similarity). Involved in CIART-mediated transcriptional repression of the circadian transcriptional activator: CLOCK-BMAL1 heterodimer (By similarity). Required for the transcriptional repression of circadian target genes, such as PER1, mediated by the large PER complex or CRY1 through histone deacetylation (By similarity). In addition to protein deacetylase activity, also has protein-lysine deacylase activity: acts as a protein decrotonylase and delactylase by mediating decrotonylation ((2E)-butenoyl) and delactylation (lactoyl) of histones, respectively.
Synonyms: HD1; RPD3L1; GON-10; KDAC1; RPD3
Tractability: Small molecule: an approved drug acts on it; a structure with a bound ligand is known; a high-quality ligand is known; it belongs to a druggable protein family. PROTAC: it is named in the literature on targeted protein degradation; UniProt records ubiquitination sites on it; ubiquitination databases record sites on it; its protein half-life has been measured; a small molecule that binds it is known. Other modalities: an approved drug acts on it.
Target class: Eraser; HDAC class I; Epigenetic regulator; Histone deacetylase
Chemical probes: FK228 (high quality), JPS016, N-(4-aminobiphenyl-3-yl)benzamide, N-(4-aminobiphenyl-3-yl)nicotinamide, PD080674, PD080734, PD080767, PD080769, PD080773, PD080787, PD081031, PD081095, PD081141, PD081143, PD081159, PD081185, PD081205, PD081217, PD081267, PD081271, and 143 more
Safety:
Unwanted effects reported when the protein is acted on. In parentheses: how it was acted on, where the effect was seen, and who reports it.
Neural tube defects (inhibition; organ; source: AOP-Wiki)
Facial cartilage structures are reduced in size and morphologically distorted (inhibition; organ; source: AOP-Wiki)
Testicular atrophy (inhibition; organ; source: AOP-Wiki)
Gene: Protein-coding gene on chromosome 1 (32,291,921 to 32,333,635, forward strand). Ensembl gene ENSG00000116478.
Subcellular location: Nucleus
Subcellular location (Human Protein Atlas): Nucleoplasm
Pathways (Reactome):
Gene expression (Transcription): ERCC6 (CSB) and EHMT2 (G9a) positively regulate rRNA expression; FOXO-mediated transcription of oxidative stress, metabolic and neuronal genes; NoRC negatively regulates rRNA expression; Notch-HLH transcription pathway; RNA Polymerase I Transcription Initiation; RUNX1 regulates genes involved in megakaryocyte differentiation and platelet function; Regulation of endogenous retroelements by KRAB-ZFP proteins; Regulation of endogenous retroelements by Piwi-interacting RNAs (piRNAs)
Signal Transduction: Deactivation of the beta-catenin transactivating complex; Downregulation of SMAD2/3:SMAD4 transcriptional activity; Estrogen-dependent gene expression; Formation of the beta-catenin:TCF transactivating complex; NOTCH1 Intracellular Domain Regulates Transcription; Regulation of PTEN gene transcription; Repression of WNT target genes; SMAD2/SMAD3:SMAD4 heterotrimer regulates transcription; STAT3 nuclear events downstream of ALK signaling; p75NTR negatively regulates cell cycle via SC1
Developmental Biology: Differentiation of naive CD4+ T cells to T helper 2 cells (Th2 cells); Regulation of MITF-M-dependent genes involved in apoptosis; Regulation of MITF-M-dependent genes involved in cell cycle and proliferation; Transcriptional and post-translational regulation of MITF-M expression and activity; Transcriptional regulation of brown and beige adipocyte differentiation by EBF2
Disease: Constitutive Signaling by NOTCH1 HD+PEST Domain Mutants; Constitutive Signaling by NOTCH1 PEST Domain Mutants; Nuclear events stimulated by ALK signaling in cancer; Potential therapeutics for SARS
Cell Cycle: G0 and Early G1; G1/S-Specific Transcription; Transcription of E2F targets under negative control by DREAM complex; Transcription of E2F targets under negative control by p107 (RBL1) and p130 (RBL2) in complex with HDAC1
Chromatin organization: HDACs deacetylate histones; Interaction of NuRD complexes with transcription factors; NuRD complex assembly
Cell-Cell communication: Negative Regulation of CDH1 Gene Transcription
and 2 more pathways
Gene Ontology:
Molecular function: core promoter sequence-specific DNA binding; DNA-binding transcription factor binding; enzyme binding; histone deacetylase activity; histone deacetylase activity, hydrolytic mechanism; histone deacetylase binding; histone decrotonylase activity; NF-kappaB binding; nucleosomal DNA binding; protein binding; protein decrotonylase activity; protein lysine deacetylase activity; protein lysine delactylase activity; RNA polymerase II cis-regulatory region sequence-specific DNA binding; RNA polymerase II core promoter sequence-specific DNA binding; RNA polymerase II-specific DNA-binding transcription factor binding; transcription corepressor activity; transcription corepressor binding; chromatin binding; DNA binding; E-box binding; hydrolase activity, acting on carbon-nitrogen (but not peptide) bonds, in linear amides; Krueppel-associated box domain binding; promoter-specific chromatin binding; and 1 more
Biological process: chromatin organization; chromatin remodeling; DNA methylation-dependent constitutive heterochromatin formation; host-mediated suppression of viral transcription; negative regulation of androgen receptor signaling pathway; negative regulation of canonical Wnt signaling pathway; negative regulation of DNA-templated transcription; negative regulation of gene expression; negative regulation of gene expression, epigenetic; negative regulation of myotube differentiation; negative regulation of transcription by RNA polymerase II; positive regulation of cell population proliferation; positive regulation of DNA-templated transcription; positive regulation of intracellular estrogen receptor signaling pathway; positive regulation of transcription by RNA polymerase II; regulation of transcription by RNA polymerase II; cellular response to platelet-derived growth factor stimulus; circadian regulation of gene expression; embryonic digit morphogenesis; epidermal cell differentiation; eyelid development in camera-type eye; fungiform papilla formation; hair follicle placode formation; heterochromatin formation; negative regulation of apoptotic process; and 11 more
Cellular component: chromatin; cytosol; histone deacetylase complex; nucleoplasm; nucleus; NuRD complex; protein-containing complex; Sin3-type complex; transcription repressor complex; cytoplasm; heterochromatin; neuronal cell body; ribonucleoprotein complex; transcription regulator complex
Genetic constraint (gnomAD): Loss-of-function variants: 12 observed, 36.78 expected, observed/expected ratio (o/e) 0.33, 90% interval 0.21 to 0.53. The upper end of that interval is the gene's LOEUF score, 0.53, which puts it in group 2 of 6, group 1 being the genes least tolerant of losing a copy. Missense variants: 277 observed, 431.13 expected, observed/expected ratio (o/e) 0.64, 90% interval 0.58 to 0.71. Synonymous variants: 142 observed, 162.38 expected, observed/expected ratio (o/e) 0.87, 90% interval 0.76 to 1.
Gene-disease validity (ClinGen):
ClinGen rates the evidence that HDAC1 causes each of these diseases.
congenital heart disease (autosomal dominant): Disputed. A heart disease that is present at birth.
Homologues: Orthologues: chimpanzee HDAC1 (99% identical), macaque HDAC1 (99% identical), mouse Hdac1 (99% identical), dog HDAC1 (99% identical), guinea pig HDAC1 (99% identical), rat Hdac1 (99% identical), rat Hdac1l (98% identical), rabbit HDAC1 (95% identical), tropical clawed frog hdac1 (91% identical), zebrafish hdac1 (90% identical), pig HDAC1 (89% identical), Caenorhabditis elegans F43G6.4 (9% identical), and 2 more. Paralogues in human: HDAC2 (86% identical), HDAC3 (53% identical), HDAC8 (33% identical), HDAC4 (26% identical), HDAC5 (26% identical), HDAC9 (25% identical), HDAC7 (23% identical), HDAC6 (22% identical), HDAC11 (16% identical), HDAC10 (11% identical).
Diseases named in the same sentence as HDAC1 in open-access papers:
HDAC1 is named in the same sentence as 358 diseases in open-access papers, as found by Europe PMC text mining. Sharing a sentence is not in itself a finding about the gene and the disease. The quoted sentences say what the papers report.
breast cancer (203 papers, 2005 to 2025). A primary or metastatic malignant neoplasm involving the breast. "HDAC1, in turn, is a recognized transcriptional suppressor of estrogen receptor α (ERα) and is associated with breast cancer." (PMID 40940954, 2025). "In the analysis of the groups with mammary carcinomas, both groups G3 and G4 showed a significant difference between subgroups concerning the positive association of HDAC1 and HDAC2 (p < 0.05)." (PMID 40590021, 2025). "Epigenetic modifications associated with the overexpression of HDAC1 also play a causal role in the progression of breast cancer (BC)." (PMID 37834214, 2023). "In breast cancer cells and osteosarcoma, HDAC1 knockdown causes cell cycle arrest and cell growth inhibition and increases the proportion of apoptotic cells, while HDAC1 overexpression promotes prostate cancer cell proliferation." (PMID 37553876, 2023). "We next determined the role of the histone deacetylase activity of HDAC1 in suppression of EMT-associated effects in breast carcinoma organoid." (PMID 37414747, 2023). "Expression of the sumoylation-defective SnoNKdR reduced the ability of HDAC1 to suppress TGFβ-induced EMT-associated invasive growth of the breast carcinoma-derived organoids." (PMID 37414747, 2023). "HDAC1 over-expression was discovered to prolong the OS time in Asian breast cancer patients, while it was a risk factor for patients with lung cancer." (PMID 35252174, 2022). "Patients with breast cancer exhibiting upregulated HDAC1 levels are associated with better DFS than OS." (PMID 35453496, 2022). "A further study showed that combination of sulforaphane and withaferin A, another natural compound, significantly causes down-regulation of overexpressed DNMT3a, DNMT3b, and HDAC1 and breast cancer cell death." (PMID 32903500, 2020). "The overexpression of HDAC1 was also associated with cell proliferation in breast cancer, cancer stem cells, and prostate cancer." (PMID 29312619, 2017). "However, in a previous study, we found an association between lower HDAC1 expression and the presence of lymph node metastases in dogs with mammary tumors." (PMID 40590021, 2025). "In addition, immunofluorescence assay showed that ZN444B inhibited the association of HDAC1 with Sp1 in breast cancer cells." (PMID 39010083, 2024). "Furthermore, the overexpression of HDAC1 has been linked to negative regulation of ER-α, suggesting a potential role for HDACs in modulating breast cancer progression by regulating ER-α levels and activity." (PMID 39008483, 2024). "In MCF-7 breast cancer cells, HDAC1 interacts with CPT1A variant 2 (CPT1AV2)." (PMID 37884951, 2023). "In addition, many studies have shown that HDAC1 is also a good diagnostic or prognostic signature for lung cancer, gastric cancer, glioma, breast cancer, and other cancers." (PMID 36172179, 2022). "Evidence exists that the knockdown of HDAC1, which is a basal-like subtype-specific driver gene, could cause cell cycle arrest, growth inhibition and apoptosis in breast cancer cells." (PMID 23579546, 2013). "Moreover, the potential involvement of HDAC1 in the ERBB2 promoter transcriptional repression is in agreement with previous studies associating HDAC1 expression with breast cancer progression and survival." (PMID 23421821, 2013). "Moreover, expression of HDAC1 mRNA was associated with clinicopathologic factors such as tumor size and histologic grade in human breast cancer, gastric cancer and glioblastoma." (PMID 23110995, 2012). "HDAC1 was also shown to induce proliferation and migration of breast cancer cells by upregulating Interleukin (IL)-8 signaling." (PMID 40165290, 2025).
breast cancer (continued). "Another lncRNA, MIR497HG, is suppressed by ZEB1-mediated recruitment of DNMT3B and HDAC1/2 in endocrine-resistant breast cancer; meanwhile, ERα enhances its expression in sensitive conditions, affecting the PI3K/Akt pathway via miR-195/497." (PMID 40843360, 2025). "Chidamide selectively binds to and inhibits HDAC1, 2, 3, and 10, proving effective as an anti-tumor agent in various cancers, including multiple myeloma, non-small cell lung cancer, and breast cancer." (PMID 41326348, 2025). "Entinostat another HDAC inhibitor targeting HDAC1, 2, and 3 coupled with Exemestane in postmenopausal women with ER+ advanced breast cancer demonstrated good safety and promising results in the ENCORE301 randomized phase II study, with increased PFS and OS." (PMID 41154396, 2025). "Recently, Tucidinostat (also known as Chidamide), a selective HDAC1, 2, 3, and 10 inhibitor, has been trialed in combination with Exemestane in advanced hormone receptor-positive (HR+) breast cancer patients to combat acquired resistance." (PMID 41154396, 2025). "A novel coumarin–hydroxamate hybrid (St.10) was designed through a pharmacophore fusion strategy to enhance HDAC1 inhibition and overcome the limitations of current HDACi in breast cancer therapy." (PMID 41440016, 2025). "These seemingly contradictory results can be explained by the study illustrating that HDAC1 has distinct substrates in different breast cancer cell lines, highlighting the effects of tumor heterogeneity on HDAC functions." (PMID 40165290, 2025). "HDAC1 inhibition using its inhibitor entinostat dramatically boosted the antitumor efficiency of anti-PD1 therapy in breast cancer." (PMID 39133578, 2024). "Direct repression or inactivation of HDAC7 through HDAC1 and HDAC3 inhibition downregulates multiple super‐enhancers (SEs) and SE‐associated oncogenes, suppressing cancer stem cell phenotypes in breast cancer." (PMID 38827027, 2024). "Collectively, these results suggest that ZN444B is a novel coumarin-derived HDAC1 inhibitor with optimal anti-tumor activity for breast cancer." (PMID 39010083, 2024). "The results showed that PARP1 and HDAC1 were markedly overexpressed in human breast cancers relative to healthy tissues, especially in TNBC." (PMID 38182579, 2024). "We performed anti-breast cancer analysis of selected YF349 derivatives with HDAC1 inhibitory IC50 values less than 1 nM to identify their structure-activity relationship (SAR)." (PMID 39010083, 2024). "Collectively, these findings provide evidence that targeting DNMT1 and HDAC1 enhances the expression of PD-L1, and the concurrent administration of an anti-PD-L1 agent represents a novel approach for the treatment of breast cancer." (PMID 38490978, 2024). "The results showed that DNMT1 and HDAC1 expression was significantly upregulated in breast cancer tissues vs. normal tissues." (PMID 38490978, 2024). "Given these insights, the GATA4/p65/HDAC1 complex emerges as a promising therapeutic target for breast cancer." (PMID 38653973, 2024). "Among all the compounds with inhibitory activity on both HDAC1 and two breast cancer cell lines, compound ZN444B displays the highest anti-proliferative activity, therefore, ZN444B was chosen for further biological evaluation." (PMID 39010083, 2024). "It was found that histone deacetylase 1 activity has a positive correlation with BCRP expression in placental breast cancer cells." (PMID 37834214, 2023). "Entinostat is an oral inhibitor of class I histone deacetylases (HDAC1) that shows a potent antiproliferative effect in breast cancer." (PMID 36717859, 2023). "For example, in breast cancer, HDAC1 deacetylated SREBP1 and inhibited E-calmodulin transcription, thereby suppressing the EMT." (PMID 37760477, 2023). "One of the 65 new breast cancer risk loci identified via GWAS—rs4971059—is shown to activate the expression of ubiquitin ligase TRIM46, which targets histone deacetylase HDAC1 for ubiquitination and degradation." (PMID 37175659, 2023).